LINC01956 (long independently transcribed non-coding RNA 1956)
Synonyms: RP11-19E11.1
Gene: Long non-coding RNA gene on chromosome 2 (118,766,965 to 118,836,088, reverse strand). Ensembl gene ENSG00000258910.
Diseases named in the same sentence as LINC01956 in open-access papers:
LINC01956 is named in the same sentence as 1 disease in open-access papers, as found by Europe PMC text mining. Sharing a sentence is not in itself a finding about the gene and the disease. The quoted sentences say what the papers report.
breast carcinoma (1 paper, 2024). "We further evaluated the associations between predicted gene expression and risk of breast cancer by subtypes and identified two genes, EN1 and LINC01956 (for ER-negative and TNBC), showing an association at the Bonferroni-corrected significance level." (PMID 38697998, 2024). "We identified four new genes (CTD-3080P12.3, EN1, LINC01956, and NUP210L) showing a significant association with breast cancer risk at the Bonferroni-corrected significance level." (PMID 38697998, 2024). "These three genes (CTD-3080P12.3, EN1, and LINC01956) have not been previously identified in TWAS for breast cancer risk." (PMID 38697998, 2024). "At Bonferroni-corrected P < 0.05, we identified six genes associated with breast cancer risk, including four genes not previously reported (CTD-3080P12.3, EN1, LINC01956 and NUP210L)." (PMID 38697998, 2024).